LASP1 (LIM and SH3 protein 1)
Diseases named in the same sentence as LASP1 in open-access papers (continued):
Sharing a sentence is not in itself a finding about the gene and the disease.
tumor (continued). "When LIM and SH3 protein 1 (LASP-1) is downregulated, it may affect zyxin proteins through the upregulation of PK, inducing G2 phase accumulation in SKOV3 cells (a human OC cell line) and thereby reducing tumor growth and invasion." (PMID 38090580, 2023). "Therefore, immunotherapy using mRNA vaccines targeting previously recognized tumor antigens (AUNIP, FANCI, LASP1, PSMD8, and XPO5) could induce immune cell infiltration to reinvigorate the ISI patient’s immune system." (PMID 35846349, 2022). "Given the importance of LASP-1 function and its clinical relevance in different cancers, LASP-1 might be used as a potential molecular target for the clinical treatment of patients with different tumours." (PMID 28266596, 2017). "Furthermore, research in the mechanism found PVT1 could target genes such as LASP1, FOXM1, RSPO1, p15, p16, EZH2, TSHR, and NOP2 to promote tumor cell proliferation, migration and invasive capability in vitro." (PMID 29088881, 2017). "Considering the tumor suppressive function of LASP2 is not consistent with the promoted effect of LASP1, both of which belong to nebulin protein family, in cancer aggressiveness we expounded displayed previously, we evaluated the expression of LASP1 and LASP2 level in CRC cell lines and tissues." (PMID 28606091, 2017). "Although levels of LASP-1 expression did not correlate with histological tumour grading, c-erbB2-, estrogen- or progesterone-expression they did correlate significantly with increased tumour size and rate of nodal-positivity." (PMID 18419822, 2008). "In our present study we could demonstrate that LASP-1 is not only highly expressed in fast proliferating malignant tumor cells, but also in proliferating regenerative epidermal basal cells, while slowly proliferating dermal fibroblasts are LASP-1-negative." (PMID 17956604, 2007). "However, levels of LASP-1 expression did not correlate with average age at time point of diagnosis, histological tumor grading, c-erbB2-, ER- or PR-expression." (PMID 17956604, 2007). "In contrast to cells in a solid tissue or tumor, non-adherent circulating CML cells do not express the indispensable LASP1 shuttle partner and tight junction protein ZO2, thus explaining the lack of nuclear LASP1 in these cells." (PMID 24913448, 2014). "When examining tumour cell lines of different entities, an overall PDEF expression is observed that does not correlate per se with low LASP-1 protein concentration." (PMID 20461080, 2010).
cancer (90 papers, 2007 to 2026). A tumor composed of atypical neoplastic, often pleomorphic cells that invade other tissues. "This proposed model is consistent with clinical evidence showing that both CERS6 and LASP1 are upregulated in different types of cancer, and that high expression is associated with poor prognosis." (PMID 37345118, 2023). "LASP1, an actin-binding protein associated with actin assembly dynamics in cancer cells, which promotes invasion and metastasis, has been linked to metastatic breast cancer, hematopoietic tumors such as B-cell lymphomas, and colorectal cancer." (PMID 37894282, 2023). "The overexpression of LASP1 in different types of human cancer is associated with unfavourable prognoses for cancer patients, and RNAi knock-down of LASP1 has led to strong inhibition of the proliferation and migration of various cancer cell lines." (PMID 36672776, 2022). "The LIM and SH3 domain protein 1 (Lasp1) was originally cloned from metastatic breast cancer and characterised as an adaptor molecule associated with tumourigenesis and cancer cell invasion." (PMID 34131132, 2021). "To determine the functional consequence of CXCR4 and LASP1 on the eIF4F complex, we examined eIF4A-dependent oncogenes commonly associated with cancer." (PMID 31106142, 2019). "Other target genes of miR-218 that have been identified by previous researchers including BMI1, LAMB3, and LASP1 and the expressions of these genes were associated with the invasion or prognosis in different cancer types." (PMID 28298809, 2017). "At present, studies on LASP1 have focused mostly on human cancers, and the underlying mechanisms remain unclear." (PMID 38575125, 2024). "Further exploring the roles and associated regulatory mechanisms of LASP-1 interactors in HBV-related HCC may help us to identify candidate anti-cancer targets for treatment of the disease." (PMID 28266596, 2017). "This could be in line with the consideration that the nuclear localization of LASP-1 may be associated with a less favorable prognosis of cancer patients." (PMID 25760690, 2015). "Since its discovery, LASP1 has been shown to be overexpressed in numerous cancers, including breast, lung, and colon cancer." (PMID 38789663, 2024). "We further show that HR-HPV E7 induces LASP1 expression in both primary keratinocytes and cancer cell lines." (PMID 38789663, 2024). "Of those, the present study focused on LASP1, because that protein has been shown to have actin-binding activity and overexpression in various types of cancer specimens." (PMID 37345118, 2023). "Relevant studies have confirmed that LASP1 is highly expressed in a variety of malignant tumors, and affects the development, invasion and metastasis of tumors." (PMID 35379225, 2022). "The CircZFR/miR-944/LASP1 axis promotes the malignant phenotype of cancer and induces DDP resistance in cancer cells." (PMID 36077769, 2022). "Many studies have confirmed that LASP1, a downstream target gene of miRNA, which is involved in the process of a variety of malignant tumors." (PMID 35379225, 2022). "Many papers had reported that the PI3K/AKT pathway was activated by LASP1 in many types of cancer cells." (PMID 36091823, 2022). "While stable miR-203 expression suppresses LASP1 and survivin, nanoliposomal delivery suppresses BMI1, indicating that suppression of distinct mRNA target profiles can lead to loss of cancer cell migration." (PMID 34449670, 2021). "In 1995, LIM and SH3 domain protein 1 (LASP1) was firstly identified with high gene expression in malignant cancer tissues by Tomasetto." (PMID 34912481, 2021). "LIM and SH3 protein 1 (LASP-1) is a direct target gene for HIF-1α, associated with actin assembly dynamics in cancer cells." (PMID 33436044, 2021).
cancer (continued). "LASP1, an actin-binding structural protein, is a nuclear transcriptional regulator in various cancers." (PMID 34124372, 2021). "In recent two decades, as the number of reports increased, the understanding of the physiological and pathological functions of LASP1 has been deepened and widened, especially in the view that LASP1 has the potential to become a cancer biomarker." (PMID 34912481, 2021). "Simultaneously, ECHS1 tends to interact with the SH3 domain at the C terminus of LASP1 to stimulate ceramide metabolism and cancer aggressiveness." (PMID 34615856, 2021). "Overall, the Let-7a targets impacted by the LASP1-Ago2 interaction are involved in cancer progression, therapy resistance and metastasis." (PMID 32872485, 2020). "Previous studies have stated that LASP1 was increased significantly in multiple malignant tumors and is involved in the development of cancers." (PMID 33074595, 2020). "Our results suggest a novel role for the LASP1-Ago2 module in shaping the RNAi landscape, functionally impacting the invasive ability of cancer cells." (PMID 32872485, 2020). "The function assays suggested that LASP1 was involved in cell proliferation, migration and cycle regulation in cancer cells." (PMID 31372094, 2019). "In the functional assays, overexpression of LASP1 recovered MIAT silencing induced cell proliferation, invasion and cycle inhibition, suggested that MIAT relied on regulation of LASP1 to regulate PTV cancer progression." (PMID 31372094, 2019). "Previous studies manifested that dysregulation of microRNAs led to LASP1 overexpression in cancer cells." (PMID 31372094, 2019). "LASP1 was also up-regulated and functioned as an oncogenic protein in many malignant tumors by regulating cell proliferation and metastasis, cell cycle transition, and apoptosis." (PMID 30988074, 2019). "The upregulation of LASP1 is observed in many malignant tumors, which suggests the oncological and clinical significance of LASP115." (PMID 29531214, 2018). "Recent studies identified LASP1 as an oncogenic gene in various types of cancer and showed that LASP1 strongly promoted the migration, invasion, and epithelial-mesenchymal transition abilities of cancer cells." (PMID 29980193, 2018). "LIM and SH3 protein 1 (LASP1) is upregulated in several types of human cancer and implicated in cancer progression." (PMID 29980193, 2018). "Again, a complex of LASP1 with dynamin and F-actin, is observed and studies promote a fractionated release of vesicular MMPs into the surrounding tissue, endowing cancer cells with increased invasiveness." (PMID 30298118, 2018). "As we know, LASP1 is an actin-binding phosphoprotein that is overexpressed in several cancers and it is a cAMP- and cGMP-dependent signaling protein which binds to the actin cytoskeleton at extensions of the cell membrane." (PMID 30326930, 2018). "Taken together, these results indicate that elucidating the interaction of LASP-1 with its binding partners will help us to further understand the molecular mechanism of LASP-1 on the development of different types of cancer." (PMID 28266596, 2017). "Our data was consistent with the previous studies that Lasp1 was overexpressed in different types of malignant tumors and significantly correlated with proliferation and invasion." (PMID 29088849, 2017). "LASP1, the LIM and SH3 protein-1, is a scaffold protein which mediates cell migration, proliferation and survival in various cancer entities." (PMID 28982387, 2017). "Overexpression of Lasp1 has been shown to correlate with multiple clinicopathological features in various types of human cancer." (PMID 29088849, 2017). "Further experiments will address this interesting, potential regulatory impact of LASP1 on transcriptional activity and cancer progression." (PMID 27588391, 2016).
cancer (continued). "Zymography assays and Western blot analysis revealed an additional promotion of MMP secretion into the extracellular matrix by LASP1, thus, most likely, altering the microenvironment during cancer progression." (PMID 27588391, 2016). "In this review we summarize published data on structure, regulation, function, and expression pattern of LASP1, with a focus on its role in human cancer and as a biomarker protein." (PMID 25622104, 2015). "In various cancers, LASP-1 is overexpressed, it influences the aggressive behavior of the cells promoting proliferation, migration, invasion and metastasis." (PMID 25760690, 2015). "LASP1 is a nucleo-cytosolic shuttling protein involved in migration, adhesion, proliferation and cell cycle progression of many cancers." (PMID 24980827, 2014). "LASP-1 overexpression was associated with larger tumors and aggressive phenotypes in ccRCC, and silencing of LASP-1 expression inhibited cancer cell migration in vitro." (PMID 24955835, 2014). "Although LASP1 is expressed at low basal levels in virtually all normal human tissues, protein overexpression has been observed in several cancer entities e.g. breast, ovarian, colon, prostate, liver, and bladder carcinoma as well as medulloblastoma." (PMID 24913448, 2014). "Recent data have demonstrated that high LASP-1 expression in cancers is essential for cancer cell proliferation, progression and metastasis." (PMID 24955835, 2014). "LIM and SH3 protein 1 (LASP-1) has been demonstrated to play an important role in cancer development and progression." (PMID 24955835, 2014). "As LASP1 is overexpressed in several cancer entities, we assessed the LASP1 mRNA expression pattern in publicly available microarray datasets." (PMID 24980827, 2014). "LIM and SH3 protein 1 (LASP-1) is a specific focal adhesion protein involved in several malignant tumors." (PMID 24386158, 2013). "An increased level of Lasp-1 protein in carcinoma cells supports their motility and invasive character, whereas a reduced Lasp-1 expression inhibits chemotactic-induced migration of cultivated kidney cells." (PMID 22514729, 2012). "Silencing of LASP-1 by RNA-interference in various cancer cell lines resulted in strong inhibition of proliferation and migration with cell cycle arrest in G2/M-phase." (PMID 20461080, 2010). "Further studies will define the potential of LASP-1 as an independent marker for diagnosis of cancer, as well as a marker for prognosis of this disease." (PMID 17211471, 2007). "In summary, our observations suggest an expanded role for LASP-1 in proliferation and cancer cell migration." (PMID 17211471, 2007). "Further prospective studies will be necessary to define the potential of LASP-1 as an independent marker for diagnosis of cancer as well as a marker for prognosis of this disease." (PMID 17956604, 2007). "However, current data suggests that LASP1 is a potential oncogene in several cancers and has a diverse array of cellular functions, such as the regulation of cell signalling and gene expression." (PMID 38789663, 2024). "This suggests that LASP1 is a major miR-203 target in these cancers." (PMID 38789663, 2024). "LASP1 inhibits the sensitivity of cancer cells to chemicals." (PMID 36175921, 2022). "Other studies have confirmed that LASP1 is highly expressed in a variety of malignant tumors such as ovarian cancer, liver cancer, colorectal cancer, and pancreatic cancer, and is closely related to the occurrence, development, invasion and metastasis of tumors, and is regarded as an oncogene." (PMID 35379225, 2022). "Since LASP1 plays a role in favouring cell proliferation and the migration of human cancer cells and few data on apoptosis have been reported, we tested the effects of Lasp1 silencing on apoptosis to explore its biological role in zebrafish embryonic development." (PMID 36672776, 2022).
cancer (continued). "Moreover, previous studies have proposed that LASP1 is an oncogene; it can promote tumorigenesis and has a great prognosis value in variety of cancer patients." (PMID 33990203, 2021). "The reason for this phenomenon maybe was that the regulatory mechanism of LASP1 in cell cycle was discrepant in various cancers." (PMID 33281873, 2020). "This role of LASP1 in cancer suggests a critical role in cancer progression and metastasis." (PMID 32872485, 2020). "The LIM and SH3 domain protein 1 (LASP1) has recently been identified as a novel BCR‐ABL substrate and is associated with proliferation, migration, tumorigenesis and chemoresistance in several cancers." (PMID 31957290, 2020). "In contrast with the si-hsa_circ_0004370 and miR-1294 inhibitor groups, cotransfection of the two molecules obviously attenuated the changes in the mRNA level of LASP1 in both cancer cells, confirming that hsa_circ_0004370 positively regulating LASP1 through down-regulating miR-1294." (PMID 30988074, 2019). "In several cancer types, an overexpression of LASP1 has been reported." (PMID 30298118, 2018). "LASP1 expression in human carcinoma and its regulation by microRNAs." (PMID 30298118, 2018). "As we have demonstrated that PVT1 affect the expression of the miR-203 and miR-203/LASP1 axis has been reported in various human cancers, it was thus reasonable to hypothesize that expression of LASP1 may be affected by dysregulated PVT1." (PMID 28404954, 2017). "Presently, it is urgent to uncover the molecular mechanism of LASP1 during cancer progression, which may contribute significantly to the development of new diagnostic strategies and potential drugs targets." (PMID 27181092, 2016). "Furthermore, LASP1 overexpression contributes to cancer aggressiveness hinting to a potential value of LASP1 as a cancer biomarker." (PMID 25622104, 2015). "Moreover in HCC, LASP1 enhanced cell proliferation and migration, thus leading to more aggressive cancer cell phenotypes, while LASP1 knockdown in HBx-expressing HepG2 and Huh-7 cells significantly suppressed hepatocellular cell proliferation and migration." (PMID 25622104, 2015). "In addition, we provide a comprehensive transcriptome analysis of published microarrays (n=2,780) that illustrates the expression profile of LASP1 in normal tissues and its overexpression in a broad range of human cancer entities." (PMID 25622104, 2015). "Thus, there is a striking contrast in the functional effects between murine Lasp1 knockout primary cells and human cancer cell lines." (PMID 25622104, 2015). "Interestingly, miR-203 was found to inhibit invasiveness of cancer cells, reducing their migration via down-regulation of LIM and SH3 domain protein 1 (LASP1,)." (PMID 26546342, 2015). "Overexpression of LASP1 has been described in several types of cancers." (PMID 25196260, 2014). "However, gene transfection-mediated overexpression of LASP1 in SW480 CRC cells resulted in aggressive cancer cell phenotypes and promoted cancer growth and metastasis (in contrast with the phenotypes induced by miR-1 restoration)." (PMID 25196260, 2014). "Silencing of LASP1 by RNA interference in various cell lines results in a strong inhibition of proliferation and migration with cell-cycle arrest in G2/M phase, whereas overexpression increased cancer cell proliferation and cell motility." (PMID 24913448, 2014). "Furthermore, LASP1 expression and nuclear localization significantly correlates with poor outcome of cancer patients." (PMID 24913448, 2014). "Moreover, LASP1 overexpression correlates with adverse outcome in these cancer entities suggesting an oncogenic function of LASP1." (PMID 24980827, 2014). "Recent studies have demonstrated LASP-1 together with another focal adhesion protein plays an important role in G2/M transition by inhibiting cdc2, suggesting its possible relation to cell-cycle in cancer." (PMID 24386158, 2013).